UBE2C (ubiquitin conjugating enzyme E2 C)
Diseases named in the same sentence as UBE2C in open-access papers (continued):
Sharing a sentence is not in itself a finding about the gene and the disease.
endometrial cancer (19 papers, 2020 to 2024). Primary or metastatic malignant neoplasm involving the endometrium (mucous membrane that lines the endometrial cavity). "UBE2C was significantly highly expressed in endometrial carcinoma, and its expression level was associated with advanced FIGO staging and poor prognosis." (PMID 31942195, 2020). "Genomic alterations and biological role of UBE2C were investigated to explore the potential mechanisms underlying its overexpression in oncogenesis of endometrial carcinoma." (PMID 31942195, 2020). "Furthermore, studies showed that UBE2C was upregulated in endometrial cancer and associated with advanced histologic grade, FIGO stage, recurrence, and shorter overall survival." (PMID 34858987, 2021). "In endometrial cancer, autophagy is critical for inducing apoptosis, hence UBE2C’s regulation of autophagy affects the autophagy-apoptosis interplay." (PMID 39403142, 2024). "The ubiquitin-conjugating enzyme E2C (UBE2C) promotes the malignant progression of endometrial cancer by inhibiting autophagy." (PMID 39403142, 2024). "Overexpression of UBE2C enhances cell proliferation, cell migration, and invasion in endometrial cancer." (PMID 38102624, 2023). "The aim of this study is to detect the expression of UBE2C, WNT5α, and E-cad in endometrial cancer (EC) and their clinical significance." (PMID 37335710, 2023). "Compared with normal adjacent endometrial tissues (n = 20), UBE2C was significantly upregulated in matched endometrial carcinoma tissues (n = 20)." (PMID 37803076, 2023). "Previous studies have identified high UBE2C expression in several types of cancer, including head and neck squamous cell carcinoma, gastrointestinal and endometrial cancer." (PMID 35124721, 2022). "Depletion of UBE2C inhibits endometrial cancer cell proliferation, migration, invasion, and epithelial–mesenchymal transformation (EMT), whereas UBE2C overexpression exerted opposite effects." (PMID 34858987, 2021).
endometrial cancer (continued). "Multivariate analysis showed that UBE2C expression (p=0.047), FIGO staging(p=0.000), lymphatic metastasis (p=0.001) and myometrial invasion (p=0.003) were independent risk factors in predicting the prognosis of endometrial carcinoma patients." (PMID 31942195, 2020). "As for UBE2C, suppression of UBE2C expression restrained E2-promoted invasion, migration and epithelial mesenchymal transition in vitro and in vivo, and UBE2C elevation was significantly correlated with higher histologic grade, recurrence, and worse OS in endometrial cancer." (PMID 37056778, 2023). "Furthermore, in vitro experiments showed that the interference of UBE2C inhibited the migration and invasion of endometrial cancer cells, while partially impact cell proliferation and didn’t impact the expression of epithelial-mesenchymal transition (EMT) markers." (PMID 37803076, 2023). "Consequently, we infer UBE2C and its relevant genes may act on DNA duplication and then affect the cell cycle, proliferation and apoptosis of endometrial carcinoma cells." (PMID 31942195, 2020). "UBE2C could act as an independent predictor for the prognosis of endometrial carcinoma." (PMID 31942195, 2020). "In additionally, overexpression of UBE2C promoted cell proliferation, migration/invasion, and epithelial–mesenchymal transition (EMT) in endometrial cancer." (PMID 38102624, 2023). "UBE2C knockdown also inhibited cell proliferation, migration, invasion, and epithelial-mesenchymal transition (EMT) in endometrial cancer, whereas overexpression exerted the opposite effects." (PMID 35332135, 2022). "Furthermore, another study revealed a positive correlation between UBE2C expression levels and tumor stage, local lymph node metastasis, and FIGO stages in endometrial cancer (EC) through IHC examinations." (PMID 38577722, 2024). "Recently, a study has demonstrated that UBE2C upregulation was relevant to the advanced histologic grade, FIGO stage, and recurrence and might be a new biomarker for the diagnosis and therapy of endometrial cancer." (PMID 34950739, 2021). "The association and the regulatory mechanisms of E2F family of transcription factors with UBE2C, MYC with UBE2C and the roles they play in the carcinogenesis of endometrial carcinoma have not been investigated, which offers new direction for the current research." (PMID 31942195, 2020).
cervical cancer (18 papers, 2009 to 2023). A primary or metastatic malignant neoplasm involving the cervix. "We evaluated the role of UBE2C in HPV associated cervical cancer cell lines in which proliferation was impaired by UBE2C knockdown or enhanced by UBE2C overexpression." (PMID 33396624, 2020). "Compared to adenocarcinoma cervical cancer, UBE2C protein expression was more frequently associated with squamous cell carcinoma (SCC); this result was consistent with the TCGA data." (PMID 33396624, 2020). "In gastric and cervical cancer, UBE2C knockdown leads to increased apoptosis induced by cisplatin and reduced phosphorylation of ERK, AKT/PKB, and p38." (PMID 37958776, 2023). "MiR‐525‐5p was reported to inhibit cervical cancer metastasis through blocking the UBE2C and ZEB1/2 signaling pathway." (PMID 36705418, 2023). "In a previous study, treatment with CCI779 (mTORC1 complex inhibitor) inhibited UBE2C expression and tumour growth in cervical cancer in vitro and in vivo." (PMID 35615976, 2022). "The depletion of UBE2C reduced cervical cancer cell proliferation by inhibiting the mTOR/PI3K/AKT pathway." (PMID 34858987, 2021). "As reported by a previous literature, miR-525-5p was verified to be a tumor suppressor in cervical cancer via hampering epithelial-to-mesenchymal transition and anoikis resistance through UBE2C/ZEB1/2 signaling pathway." (PMID 34507559, 2021). "Overexpression and knockdown of UBE2C enhanced and reduced cervical cancer cell proliferation, respectively, in vitro." (PMID 33396624, 2020). "In this study, TMA data demonstrated that a high proportion (89.4%) of cervical cancer cases exhibited a high expression level of UBE2C protein, which was supported by the gene profiling assay of UBE2C gene expression in cervical cancer tissue." (PMID 33396624, 2020). "At present, the expression of UBE2C in cervical cancer and its relationship with HPV are still unclear." (PMID 33396624, 2020). "The Cancer Genome Atlas (TCGA) indicates that patients with cervical cancer with high UBE2C/cancer marker co-expression levels have a poor prognosis." (PMID 33396624, 2020). "In vitro analysis showed that proliferation of HeLa cervical cancer cells was enhanced by overexpression of UBE2C, but it was impaired by knockdown of UBE2C and UBE2C inhibitors." (PMID 33396624, 2020). "To understand the role of UBE2C in HPV positive cervical cancer cells, we measured the expression of UBE2C in HeLa cells (HPV18 genome), and CaSki and CC7T/VGH cells (both contain the HPV16 genome) by immunoblotting." (PMID 33396624, 2020). "TMA revealed that UBE2C was highly expressed in cervical cancer specimens and the expression levels correlated with BMI values and cervical cancer cell types." (PMID 33396624, 2020). "UBE2C will need to be studied further to assess its potential as a target for the treatment of cervical cancer." (PMID 21338529, 2011). "MMP3, UBE2C and p16 protein overexpression in cervical cancers was confirmed by immunohistochemistry." (PMID 21338529, 2011). "Immunohistochemistry was used to study the protein expression of MMP3, UBE2C and p16 in normal, dysplasia and cancers of the cervix." (PMID 21338529, 2011). "Two of the genes of this signature, AURKA and UBE2C, were validated in human breast and cervical cancer as potential biomarkers of malignancy." (PMID 20630075, 2010). "mRNA levels of UBE2C were found to be significantly increased in cervical cancer, indicating that these proteins may have potential carcinogenic effects." (PMID 33396624, 2020). "UBE2C could be evaluated further to assess its potential as a therapeutic target in cervical cancer." (PMID 21338529, 2011). "In cervical cancer, UBE2C was reported to be a target gene of miR-525-5p, and overexpression of miR-525-5p dramatically repressed cell viability, invasiveness, and migration ability; elevated the expression of UBE2C; and partially blunted the salutary effects of miR-525-5p on invasive ability." (PMID 34858987, 2021).
cervical cancer (continued). "Recent studies have also found that UBE2C/ZEB1/2 signal axis plays an important role in the metastasis and AR in cervical cancer." (PMID 37081871, 2023). "Treatment of cervical cancer cells with vorinostat, a histone deacetylase inhibitor that reduces PI3K/AKT/mTOR signaling and UBE2C activation, reverses EMT through downregulation of N-cadherin and vimentin and upregulation of E-cadherin." (PMID 37958776, 2023). "It was also demonstrated that UBE2C plays a pivotal role in the regulation and activation of the mTOR/PI3K/AKT pathway in cervical cancer." (PMID 35124721, 2022). "In addition, UBE2C may serve as a target for treatment of cervical cancer in the future." (PMID 33396624, 2020). "Recently one study found several novel genes to be differentially expressed in cervical cancer and was overexpressed in cervical cancers, confirmed by immunohistochemistry such as MMP3, UBE2C and p16 protein." (PMID 23505442, 2013). "Our results suggest that UBE2C is a critical factor in HPV-related cervical cancer; thus, it could be a useful novel tumor marker for accurately identifying patients with cervical cancer." (PMID 33396624, 2020).
colon cancer (17 papers, 2009 to 2024). "UBE2C overexpression accelerates the proliferation of colon cancer by alternating the cell cycle profile." (PMID 32899896, 2020). "Other reports show that expression of UBE2C is elevated in breast, thyroid, and colon cancer, and in lymphoma." (PMID 27528424, 2016). "In colon cancer, miR-381 inhibits UBE2C and, as a result, suppresses cell growth." (PMID 33324542, 2020). "A previous study detected a higher expression of UBE2C in advanced colon cancer." (PMID 33324542, 2020). "The inhibition of UBE2C by NSC697923 promoted CEMIP down-regulation, increasing the sensitivity to radiotherapy in the SW480 colon cancer cells." (PMID 31213644, 2019).
esophageal squamous cell carcinoma (14 papers, 2018 to 2025). Esophageal squamous cell carcinoma (ESCC) is a type of esophageal carcinoma (EC) that can affect any part of the esophagus, but is usually located in the upper or middle third. "The inhibition of proliferation and promotion of apoptosis caused by UBE2C knockdown was also detected in esophageal squamous cell carcinoma." (PMID 35332135, 2022). "For example, FOXM1 is a validated transcription factor of UBE2C in esophageal squamous cell carcinoma." (PMID 36765911, 2023). "This study aimed to elucidate the molecular mechanism of ubiquitin conjugating enzyme E2 C (UBE2C) in esophageal squamous cell carcinoma (ESCC)." (PMID 34488675, 2021). "Therefore, the aim of this study was to investigate whether UBE2C is a transcriptional target of FOXM1, using esophageal squamous cell carcinoma (ESCC) as a model, in addition to several cancer-deposited data." (PMID 29596365, 2018).
lung adenocarcinoma (14 papers, 2010 to 2024). A carcinoma that arises from the lung and is characterized by the presence of malignant glandular epithelial cells. "The mechanism of action of UBE2C in lung adenocarcinoma (LUAD) and its significance in cancer diagnosis, targeted therapy and immunotherapy, even in pan-cancer, are still unclear." (PMID 38370368, 2024). "The results explained that the high expression of UBE2C, UCHL1, TRAIP, TNNT1, TNNI3, and RAC3 were associated with poor overall survival of lung adenocarcinoma patients (p < 0.05)." (PMID 33050659, 2020). "Immunohistochemical analysis demonstrated the up-regulation of the protein levels of Mcm2, Fen1, Ube2C and cyclin D1 in lung adenocarcinoma tissue of NNK-exposed Gprc5a-knockout mice compared to the levels in normal lung tissue obtained from the same mice." (PMID 20686609, 2010). "It has been reported that the expression of UBE2C and MYBL2 was significantly positively correlated in a variety of cancers (including lung adenocarcinoma, lung squamous cell carcinoma, etc.)except GC." (PMID 37840753, 2023). "UBE2C was significantly upregulated in LUAD (lung adenocarcinoma) and LUSC (Lung squamous cell carcinoma) compared to the normal tissues." (PMID 34257576, 2021).
liver cancer (12 papers, 2018 to 2024). An epithelial or non-epithelial malignant neoplasm that arises from the liver. "Recent studies showed that overexpression of UBE2C is associated with various cancers such as breast, colon, lung, and liver cancers." (PMID 34577856, 2021). "In liver cancer, UBE2C has been identified as a potential oncogene that can promote cell proliferation, migration, invasion, and drug resistance." (PMID 38463168, 2024). "Among them, ARHGEF39 and UBE2C have been reported in the literature as potential oncogenes involved in the development of liver cancer." (PMID 38463168, 2024). "As a key downstream gene of KAT2A and E2F1, we also found that UBE2C significantly inhibited the proliferation of the liver cancer cell line, HepG2, and pancreatic cancer cell line, BxPC3, through a CCK-8 assay, which suggested that UBE2C plays a critical role in pan-cancer." (PMID 36292703, 2022). "In addition, UBE2C has been found to be upregulated in liver cancer, and depletion of UBE2C obviously suppressed the proliferation, migration, and invasion of HCC and improved the sensitivity of HCC cells to sorafenib." (PMID 34858987, 2021). "Integrative analysis of gene expression differences in liver cancer further highlights three genes: ARHGEF39, UBE2C and DQX1." (PMID 38463168, 2024). "Our analysis has identified three potential oncogenes, ARHGEF39, UBE2C, and DQX1 of liver cancer." (PMID 38463168, 2024). "The results showed that UBE2C, PTTG1, TOP2A and SPP1 were positive, FCN3, SLC22A1, ADH4, CYP2C8, SLC10A1, and FBP1 were negative in liver cancer tissues." (PMID 38664521, 2024).
melanoma (12 papers, 2008 to 2025). A malignant, usually aggressive tumor composed of atypical, neoplastic melanocytes. "Protein PXDN is a melanoma-associated protein and the ubiquitin-conjugating enzyme E2C (UBE2C) is believed to play a role in tumor progression." (PMID 18173842, 2008). "Furthermore, the high mRNA expression level of UBE2C is associated with poor overall survival of patients with melanoma, according to the cancer genome atlas (TCGA) database." (PMID 33800394, 2021). "Further analysis of UBE2C expression revealed that patients with low UBE2C expression exhibited better survival outcomes, particularly in melanoma patients receiving immune checkpoint blockade (ICB) therapy, highlighting UBE2C as a potential risk gene." (PMID 40135850, 2025). "Similar results were obtained in melanoma; downregulation of UBE2C acts as a cell growth regulator via blocking ERK/Akt signalling pathways, and preventing the G2/M transition by activating MPF and stimulating apoptosis." (PMID 35124721, 2022). "The downregulation of UBE2C suppressed melanoma cell growth via the inactivation of the ERK and AKT signaling pathways and the induction of apoptosis." (PMID 33800394, 2021). "The Ub-conjugating enzyme E2-C (UBE2C), a key regulator of cell progression, is upregulated in melanomas compared to Spitz nevus." (PMID 33800394, 2021). "In melanoma, UBE2C was reported to promote the cell growth of melanoma via promotion of the G2/M transition." (PMID 34858987, 2021). "Finally, it was also shown that the knockdown of UBE2C inhibited the growth of xenografted melanoma." (PMID 33800394, 2021). "Silencing UBE2C arrests cell cycle progression at the G1/S phases, inhibits cell proliferation in pancreatic ductal adenocarcinoma and blocks the G2/M transition in melanoma." (PMID 32899896, 2020).
thyroid cancer (12 papers, 2005 to 2025). "In summary, this study suggests that PILRA, MKI67, and UBE2C may serve as both diagnostic biomarkers and therapeutic targets for breast and thyroid cancers." (PMID 41328437, 2025). "Similarly, UBE2C, encoding UbcH10, a key enzyme in cell cycle regulation, is minimally detectable in normal thyroid cells but significantly overexpressed in thyroid carcinoma cell lines." (PMID 40346322, 2025). "Previous studies have elucidated the dual role of UBE2C in thyroid cancer (THCA) as both a tumor suppressor gene and an oncogene." (PMID 38577722, 2024). "UBE2C upregulation has been found in cancers from many origins, including follicular cell–derived thyroid carcinomas." (PMID 38958823, 2024). "The present study aimed to explore the role of ubiquitin-conjugating enzyme E2 C (UBE2C) in the progress of thyroid carcinoma (THCA)." (PMID 35332135, 2022). "Survival analysis indicated that high expression of TOP2A, TYMS, FEN1, PRC1, or UBE2C gene significantly decreased disease-free survival of patients with other thyroid carcinomas." (PMID 30774662, 2019). "Further survival analysis showed that high expression of TOP2A, TYMS, FEN1, PRC1, or UBE2C gene significantly decreased disease-free survival of patients with other thyroid carcinomas." (PMID 30774662, 2019). "High expression of TOP2A, TYMS, FEN1, PRC1, or UBE2C gene significantly decreased disease-free survival of patients with other thyroid carcinomas." (PMID 30774662, 2019). "For instance, Ubiquitin-conjugating enzyme E2 C (UBE2C) participated in the progression of thyroid carcinoma (THCA), may play the dual role of both oncogene and tumor suppressor gene." (PMID 38795139, 2024). "UBE2C gene expression did not significantly change in other thyroid carcinomas (figure not shown)." (PMID 30774662, 2019).